AURKB (aurora kinase B)
Diseases named in the same sentence as AURKB in open-access papers (continued):
Sharing a sentence is not in itself a finding about the gene and the disease.
breast cancer (continued). "AURKB is most highly expressed in the triple negative subset of breast cancers." (PMID 36313574, 2022). "When these AURKB overexpressing cells were injected into nude mice, formation of mammary epithelial tumors was observed along with amplifications and deletions of DNA isolated from these mouse mammary tumors." (PMID 33915740, 2021). "Previously, decreased H3K4me3 by AKT inhibitor MK2206 in PIK3CA-mutated TNBC cells was shown to be associated with the suppressed expression of aurora kinase B (AURKB), proliferating cell nuclear antigen (PCNA) and other genes that are critical to breast cancer survival." (PMID 33664847, 2021). "In breast cancer, the level of AURKB is overexpressed and related to low survival rate of patient." (PMID 32863956, 2020). "AURKB modulates drug response in non‐small cell lung, and breast cancers." (PMID 32986937, 2020). "In the present study, we found that AME can cause S-phase arrest of breast cancer cells, downregulate the expression of CDC20, AURKB, PLK1, CCNB2, and TOP2A, and upregulate the expression of GADD45A, eventually inhibiting the proliferation of breast cancer cells." (PMID 31275405, 2019). "Interestingly, clinical data show that PLK4 and AURKB expression are increased in high-grade bladder cancer and correlate with reduced survival in breast cancer patients." (PMID 31142743, 2019). "Moreover, Inhibition of AURKB with AZD1152 inhibited the proliferation of estrogen-resistant breast cancer cells, which also sheds light on the overcome the estrogen-resistance breast cancer." (PMID 28147341, 2017). "Consistent with this, we have shown that the small molecule inhibitors GSK462364, GSK923295, and GSK1070916 that target the network proteins PLK1, CENPE, and AURKB/C, respectively, inhibit the growth of breast cancer cell lines with high MNAI at lower concentrations than cell lines with low MNAI." (PMID 27368372, 2016). "We next measured the levels of signature genes whose protein products could be pharmacologically targeted in breast cancer lines (AURKB, SUV39H1, SUV39H2 and KDM4B)." (PMID 27863398, 2016). "Therefore, our results indicate that Aurora kinase B is a driving factor for growth of antiestrogen resistant T47D breast cancer cell lines, and a biomarker for reduced benefit of tamoxifen treatment." (PMID 25885472, 2015). "Moreover, we investigated the clinical relevance of Aurora kinase B expression in primary tumors from breast cancer patients receiving tamoxifen as first-line adjuvant endocrine therapy." (PMID 25885472, 2015). "Collectively, these findings suggest that breast cancer patients resistant to antiestrogens could benefit from treatment targeting Aurora kinase B, e.g. barasertib." (PMID 25885472, 2015). "In this study we found that Aurora kinase B is an important kinase for growth and signaling in the ER-negative fulvestrant resistant T47D breast cancer cell lines and that Aurora kinase B also plays a role for growth of ER-positive tamoxifen resistant T47D cell lines." (PMID 25885472, 2015). "Based on the increased expression of AURKB and other aurora B signaling pathway members in AA tumors, we speculate that this drug may be used as an effective treatment for African American breast cancer patients." (PMID 24324792, 2013). "Recent study demonstrated that high expression of AURKB might induce EMT in breast cancer." (PMID 36199443, 2022). "Thus, inhibition of Aurora kinase B, e.g. with the highly selective kinase inhibitor barasertib, could be a candidate new treatment for breast cancer patients with acquired resistance to antiestrogens." (PMID 25885472, 2015).
breast cancer (continued). "Our analyses suggest that the deregulation of FOXM1 and AURKB pathways may contribute to the progression from hormone-dependent to hormone-independent growth of breast cancer since our results show that the activity of both pathways is higher in ER-negative, PGR-negative breast cancer." (PMID 25213199, 2014). "In breast cancer cells, MOF-mediated acetylation of AURKB enhances AURKB protein stability and promotes c-MYC phosphorylation, ultimately leading to c-MYC accumulation and increased tumor cell proliferation." (PMID 40710353, 2025). "Specifically, MOF-driven acetylation of AURKB promotes the accumulation of c-MYC, thereby facilitating malignant proliferation in breast cancer cells." (PMID 40710353, 2025). "Our study demonstrates that MOF-mediated acetylation of AURKB at K215 enhances AURKB stability and kinase activity, thereby promoting c-MYC accumulation and supporting breast cancer cell proliferation." (PMID 40710353, 2025). "In breast cancer such as TNBC, AURKB overexpression can promote EMT by activating the AKT/mTOR signaling pathway." (PMID 38886738, 2024). "In breast cancers, we found significant upregulation of KIFC1, AURKB, BIRC5, and CDCA8 in tumor samples of both the GEPIA and UALCAN datasets, compared to normal samples." (PMID 39335162, 2024). "In breast cancer datasets, we found significant upregulation of both centrosome clustering proteins KIFC1, AURKB, BIRC5, and CDCA8 and the oncogenes FOXM1, ATAD2, and E2F1 in tumor samples compared to normal samples." (PMID 39335162, 2024). "AURKB inhibitors, such as AZD2811, are currently under clinical trials in patients with solid tumors, including breast cancer." (PMID 38886738, 2024). "Results revealed that KIF11, AURKB, TPX2 and KIFC1 are essential genes whose depletion in both breast cancer cell lines impacts cell viability." (PMID 37835564, 2023). "A cancer dependency map (depmap.org) further highlighted KIF11, AURKB, RACGAP1 and TPX2 as genes with essential effects in 47 breast cancer cell lines." (PMID 37835564, 2023). "The usage of bioinformatics tolls resulted in the identification of AURKA, AURKB, TTK, MELK and KIF20A as top 5 hub genes involved in breast cancer occurrence and progression." (PMID 37231064, 2023). "GEPIA analysis disclosed that breast cancer patients have significantly higher expression of AURKA (4.0 vs. 1.5), AURKB (4 vs. 1), TTK (2.5 vs. 0.5), MELK (3.0 vs. 0.5), KIF20A (3.5 vs. 0.5) genes compared to healthy people." (PMID 37231064, 2023). "PLK1, AURKB, and survivin are overexpressed in triple-negative breast cancer (TNBC), an aggressive breast cancer subtype." (PMID 36627281, 2023). "The most common breast cancer subtype is Luminal A; NHB women with Luminal A breast cancers significantly overexpress PLK1, AURKB, and NDC80, while TBK1 is significantly overexpressed in Luminal A breast cancers from NHW women." (PMID 36494865, 2022). "Supporting this data, MELK expression levels correlate with FOXM1 RNA expression levels, as well as with the FOXM1-regulated gene, Aurora kinase B (AURKB), in TCGA breast cancer dataset." (PMID 31909186, 2020). "In this study we evaluate the potential MGMT’s role in control of therapeutic, clinically relevant, cell cycle regulators involved in breast cancer oncogenesis (CDC2, TOP2A, AURKB, CDC20, KIF20A, Cyclin A2, Cyclin B2, Cyclin D1)." (PMID 30038716, 2018). "Temozolomide alone decreases p-AURKB and p-TOP2A expression in breast cancer cells compared to controls." (PMID 30038716, 2018). "We show that O6-benzylguanine (BG), an MGMT inhibitor decreases CDC2, CDC20, TOP2A, AURKB, KIF20A, cyclin B2, A2, D1, ERα and survivin and induces c-PARP and p21 and sensitizes ER positive breast cancer to temozolomide (TMZ)." (PMID 30038716, 2018). "In breast cancer, subnetwork modules encompassing proliferation pathways (Mitosis, PLK1, AURKA, and AURKB) were highly prognostic." (PMID 30420699, 2018).
breast cancer (continued). "We measured quantitative dose responses for 53 breast cancer cell lines to inhibitors of PLK1, CENPE and AURKB/C designated GSK462364 GSK923295 and GSK1070916, respectively." (PMID 27368372, 2016). "CCNB1 mRNA expression has been reported to be significantly and positively correlated with mRNA expression levels of CENPE, AURKB, PLK1, and PLK4 in both breast tumors and breast cancer cell lines." (PMID 21445301, 2011). "Additionally, H3K4me3 demethylation has been shown to affect AURKB and E2F2 transcription levels in breast cancer tumors and is correlated with poor clinical outcomes." (PMID 36982384, 2023). "In our experiment, a significant difference in the phosphorylation level of AURKB was found between PTX-resistant breast cancer cells and wild-type cells, rather than the total expression of AURKB." (PMID 35088239, 2022). "In our study, in PTX-resistant breast cancer cells, AURKB weakened the negative transcriptional regulation of RAB27B by self-phosphorylation, while phosphorylation of AURKB further enhanced the stability of RAB27B." (PMID 35088239, 2022). "In conclusion, the overexpression of AURKB, GINS2, MCM10, UHRF1, POLE2, SPC24, and E2F2 in HER2-positive breast cancer patients with ALR showed that these hub genes could be potential prognostic biomarkers in such patients." (PMID 33013420, 2020). "At present, many studies have already indicated that AURKB is a promising therapeutic target in various cancers, such as non-small cell lung cancer (NSCLC), gastric cancer (GC), leukemia, prostate cancer (PC), and breast cancer." (PMID 31576249, 2019). "Interestingly, the analysis of breast cancer datasets revealed that the expression of PICH correlates with that of mitosis-related genes, such as KIF4A, CEP55, MKI67, MELK, BUB1, CENPA, and AURKB." (PMID 31160555, 2019). "In addition, BG+/-TMZ significantly decreased p-CDC2, p-AURKB, p-TOP2A, p-KIF20A and p-CDC20 expression in breast cancer cells." (PMID 30038716, 2018). "These genes include AURKB, BUB1, CHEK1, FOXM1, KIFC1, and TTK7, five of which, BUB1, CHEK1, FOXM1, KIFC1, and TTK, we have also identified and have functionally validated to have a selective requirement for cell growth in breast cancer cell models." (PMID 29535384, 2018). "We also show that breast cancer cell lines with high mitotic activity are preferentially sensitive to small molecule inhibitors that target mitotic apparatus proteins PLK1, CENPE and AURKB/C, designated GSK462364, GSK923295, and GSK1070916, respectively." (PMID 27368372, 2016). "Both FOXM1 and AURKB were significantly upregulated in brain metastasis samples compared to primary breast cancer samples and non-neoplastic samples." (PMID 24489661, 2014). "Also, AURKB and KIF20A, the other two genes amongst five critical genes which are introduced as pivotal targets for prospective drug discovery and inhibitor designing, were indicated to play a crucial role in breast carcinoma metastasis to the skin." (PMID 37231064, 2023). "There were negative expression correlations of hsa-let-7a-5p-CCNB2, hsa-let-7c-5p-CCNB2, hsa-let-7a-5p-AURKB, hsa-miR-30a-5p-CDC20, hsa-miR-30a-5p-MYBL2, hsa-miR-29c-3p-OIP5, hsa-miR-10b-5p-CHAF1B, hsa-miR-195-5p-CCNE1, and hsa-miR-497-5p-CCNE1 in ERα positive breast cancer." (PMID 32500028, 2020). "Importantly, our study reveals that the MOF/MSL complex promotes breast cancer cell proliferation by stabilizing the CPC through acetylation of AURKB at K215—without altering AURKB mRNA expression—highlighting the significance of post-translational regulation in tumor progression." (PMID 40710353, 2025). "Specifically, we found a significant inverse correlation between AURKB expression and IC50 of PTX in basal‐like subtype, the majority of which belong to TNBC (r = −0.9171, p = 0.0013), but not luminal breast cancer cell lines (r = −0.2609, p = 0.6175)." (PMID 40099930, 2025).
lung carcinoma (46 papers, 2010 to 2026). "Smoking is a high risk factor and driving event for lung cancer, as we found here, significantly correlated with higher expression of AURKB in LUAD." (PMID 33612479, 2021). "As early as 2005, AURKB is found to be correlated with high frequencies of somatic mutations in lung cancer." (PMID 33612479, 2021). "Previous studies have shown that AURKB overexpression is associated with tumor progression in renal cell carcinoma, lung cancer, anaplastic thyroid carcinoma, hepatocellular carcinoma, and head and neck squamous cell carcinoma." (PMID 32258155, 2020). "Here, the authors show AURKB activation to be associated with resistance in EGFR mutant lung cancer cells, and that AURKB is a therapeutic target in resistant tumours that lack the p.T790M or other acquired mutations." (PMID 31000705, 2019). "Immunohistochemistry shows that overexpression of cell division cycle associated 8 (CDCA8) and AURKB can result in bad outcome of lung cancer patients; thus, suppression of the CDCA8-AURKB pathway is a potential therapeutic strategy for lung cancer." (PMID 27610375, 2016). "Both AURKA and AURKB have been implicated in the development of lung cancer growth." (PMID 33202573, 2020). "In NCSLC, overexpression of AURKA and AURKB has been associated with poor prognosis due to reduced overall survival and both kinases have been found to either potentiate or repress chemo- and/or radiotherapy in lung cancer." (PMID 33202573, 2020). "Interestingly, AURKA and AURKB expression levels have been used as diagnostic and prognostic markers in lung cancer, suggesting that these kinases play a role in lung oncogenesis." (PMID 26842935, 2016). "The phenomenon of AURKB overexpression or increased copy number has been observed in tissues and cells of various cancers, such as lung cancer, gastric cancer, and glioblastoma." (PMID 38396874, 2024). "We found that USP29 stabilizes AURKB in gastric cancer, neuroblastoma, lung cancer and colorectal cancer." (PMID 38233848, 2024). "CENPF (Centromere protein F) is a gene related to chromosome segregation during mitosis that reduces overall survival in lung cancer and is a hub gene (AURKB, BUB1B, KIF2C, HMMR, CENPF, and CENPU) overexpressed in cancer patients." (PMID 36661515, 2023). "To date, it has been found that AURKB is highly expressed in various malignant tumors, including colon adenocarcinoma, thyroid follicular carcinoma, laryngeal carcinoma, lung cancer, and breast invasive ductal carcinoma." (PMID 35088239, 2022). "It has been reported in previous literature that NEK2, TOP2A, PLK1, CA4, and AURKB can play oncogenic or tumor suppressing roles in the progression of lung cancer." (PMID 35646063, 2022). "In brief, we found that the USP7 was highly expressed concomitantly with the mitotic factors such as PLK1, CCNB1, CDC25A, and AURKB in prostate and lung cancer." (PMID 33207738, 2020). "In vitro assays showed that GSK 1070916 conferred a dose-dependent inhibition of histone H3 phosphorylation, a specific substrate of AURKB and conveyed anti-tumor effects in ten human tumor xenografts, including lung cancer." (PMID 33202573, 2020). "After growth arrest and polyploidy, AURKB inhibition triggers cell death in lung cancer, leukemia, prostate cancer, or neuroblastoma cell but senescence in fibroblasts, endothelial or melanoma cells." (PMID 31000705, 2019). "Immunohistochemical analysis indicates AURKB, which mediates chromosome segregation during mitosis, is frequently overexpressed in primary lung carcinomas." (PMID 27610375, 2016). "The expression of AURKB has been correlated with the level of genetic instability in lung carcinoma." (PMID 27341628, 2016). "In this work we demonstrated that AURKA and AURKB are potential new promising targets for KRAS-induced lung cancer therapy." (PMID 26842935, 2016).
lung carcinoma (continued). "AURKB has garnered significant attention in cancer research due to its elevated expression in multiple malignancies, including colorectal adenocarcinoma, thyroid follicular carcinoma, laryngeal carcinoma, and lung cancer." (PMID 40710353, 2025). "–31 Moreover, AURKB expression has potentiated drug resistance in glioblastoma and lung cancer." (PMID 37079315, 2023). "AURKB mRNA expression is thought to modulate paclitaxel resistance in lung cancer." (PMID 34593983, 2023). "Furthermore, AURKB, CCNB2, CDC20, CDCA5, CDCA8, CENPF, and KNTC1 are were highly expressed in lung cancer tissues and were associated with poor prognosis." (PMID 35598017, 2022). "Overexpression of AURKB has been clarified related to a range of cancers including clear cell renal cell carcinoma, gastric cancer, leukemia, and lung cancer." (PMID 35222021, 2022). "Similar to AURKA, upregulated levels of AURKB in lung cancer have also been associated with negative prognosis and poor therapeutic response." (PMID 33202573, 2020). "Also specific to the epithelial compartment, we observed enrichment for a signature conferring poor outcome in lung cancer, which included general cancer prognostic genes like AURKB, EXO1, MAD2L1, CDCA8, and kinesins like KIF15." (PMID 32883324, 2020). "The Aurora kinases, Aurora-A (AURKA), and Aurora B (AURKB) are overexpressed in many tumor entities such as lung cancer that correlate with poor survival, whereby their inhibition, in most cases, enhances the efficacy of chemo-and radiotherapies, indicating their implication in cancer therapy." (PMID 33202573, 2020). "In order to validate AURKA and/or AURKB as therapeutically relevant KRAS targets in lung cancer, we treated A549 and H358 cells, as well as two different lung cell based models of gain-of-function of KRAS with a dual Aurora kinase inhibitor and performed functional in vitro assays." (PMID 26842935, 2016). "Additionally, a correlation between Aurora kinase B expression and poor survival has been demonstrated in several cancers including glioblastomas, head and neck squamous cell cancer and lung cancer." (PMID 25885472, 2015). "Additionally, radiotherapy sensitivity of lung cancer could be enhanced by inhibition of AURKB induced by an herbal drug Daurinol." (PMID 33612479, 2021). "Therefore, AURKB plays a critical part in lung cancer and may be a vital drug target to reverse the resistance to chemotherapy, targeted therapy, or radiotherapy." (PMID 33612479, 2021). "Finally, Aurora kinase pharmacological inhibition preferentially targets lung cancer cells expressing KRASG12V, thereby supporting our hypothesis that AURKA and AURKB are promising targets for KRAS-induced lung cancer therapy." (PMID 26842935, 2016). "Researches showed that AURKB is an important target for KRAS, therefore has the potential to serve as a target of KRAS-induced lung cancer." (PMID 33612479, 2021). "We additionally compared 7 microarrays and sequencing data sets using the lung cancer explorer (LCE) database, and the results confirmed that AURKB expression was up-regulated in lung adenocarcinoma (p=3.1e-10)." (PMID 33612479, 2021). "Silencing of AURKB validated this concept, which resulted in a marked increased resistance to paclitaxel, confirming the effect that reduced AURKB expression modulates insensitivity to taxane in human lung cancer cells and, thus, may serve as predictive parameter to taxane response in NSCLC." (PMID 33202573, 2020). "In EFV treated A549 lung cancer cells, EFV significantly decreased expression levels of both MAD2L2 (fold changes, **p < 0.01 and ***p < 0.001) and AURKB (fold changes, p < 0.001) genes at 24 h and 48 h." (PMID 33110481, 2020). "Another anti-tumor inhibitor, quercetin, showed effective inhibition of AURKB pro-tumorigenic activities by directly binding to AURKB under in vitro and in vivo conditions in JBC Cl41 and A549 lung cancer cells and A549 xenografts, respectively." (PMID 33202573, 2020).